FOXP3 (forkhead box P3)
Diseases named in the same sentence as FOXP3 in open-access papers (continued):
Sharing a sentence is not in itself a finding about the gene and the disease.
Autoimmunity (continued). "Importantly, purified populations always contain Foxp3− effector T cells (Teffs) that theoretically could exacerbate autoimmunity in the recipient." (PMID 19551149, 2009). "Treg cells are a subset of CD4+ T helper cells characterized by the expression of the transcription factor Foxp3 and the surface receptor CD25 (IL-2 receptor alpha subunit) and are key for maintaining immune homeostasis and preventing autoimmunity." (PMID 41366167, 2025). "Regulatory T cells (Tregs), which typically express FOXP3 and produce IL-10 and TGF-β, are generally responsible for suppressing autoimmunity." (PMID 41465549, 2025). "This suggests a potential mechanism where defective Treg function could lead to ongoing autoimmunity, characterized by the loss of FOXP3 expression under inflammatory conditions and induction of proinflammatory cytokines such as IL-17A and IFN-γ (IFN-γ+ FOXP3+ IL-17A+)." (PMID 38731877, 2024). "While Th17 is an important cell lineage that propagates autoimmunity, CD4+CD25+FoxP3+ Treg cells inhibit pathological autoimmunity." (PMID 37628811, 2023). "Tr1 cells and Foxp3+ regulatory T cells are highly immune‐suppressive subsets of CD4+ T cells, and they exert important suppressive and homeostasis effects on cancer, autoimmune disorders, and inflammatory responses." (PMID 35587519, 2022). "The increased methylation of the forkhead box p3 (Foxp3) promoter region in CD4+ T cells in LADA patients of Chinese can lead to a decrease in T-reg numbers and functional defects and induce LADA autoimmunity." (PMID 36090989, 2022). "Tregs expressing forkhead box 3 (FOXP3), a specialized subset of CD4+ T cells, play crucial roles in maintaining immune tolerance and preventing autoimmunity." (PMID 35720275, 2022). "In pathogenesis of autoimmunity, the concept of an insufficiency of CD4+FOXP3+ Tregs is opposed by a theory postulating their functional deficit, rather than a numerical defect of them." (PMID 36578493, 2022). "CD4+CD25+ regulatory T cells (Tregs), a subpopulation of naturally CD4+ T cells that characteristically express transcription factor Forkhead box P3 (FOXP3), play a pivotal role in the maintenance of immune homeostasis and the prevention of autoimmunity." (PMID 35474948, 2022). "miR-21 acts indirectly to positively regulate Foxp3 expression; however, in autoimmunity, reduced miR-21 expression is correlated with increased STAT3 and reduced STAT5 and Foxp3 expression." (PMID 36032083, 2022). "Other studies reported that DT-mediated depletion of Foxp3+ cells in DEREG mice induced increased division of DC and precursor DC in lymphoid organs and up-regulation of CD80, CD86 and CD40 in the context of autoimmunity." (PMID 36846549, 2022). "During acute viral infections, regulatory T lymphocytes (Tregs), a subpopulation of T cells (FoxP3+ CD4+CD25+), play an essential role in controlling inflammation and preventing autoimmunity and tissue complications by regulating immune system homeostasis." (PMID 35887067, 2022). "Forkhead box P3 (FOXP3) regulatory T cells (Tregs) play a pivotal role in the maintenance of immune homeostasis and prevention of autoimmunity." (PMID 35474948, 2022). "Foxp3+ Tregs are potent immunosuppressive CD4+ T cells that are critical to maintain immune quiescence and prevent autoimmunity." (PMID 34747370, 2021). "Among the four CNSs described for the initiation and maintenance of Foxp3 transcription, CNS2 containing Runx1-CBFβ binding sites, is the only one preventing autoimmunity." (PMID 34539668, 2021). "In contrast, other subsets that have strong implications for autoimmunity – namely, regulatory CD4+CD25+FoxP3+ Tregs – were reduced in knockout mice." (PMID 33737335, 2021).
Autoimmunity (continued). "In addition to orchestrating the molecular signaling of Th17 development, STAT3 may also inhibit Foxp3 transcription via blocking the binding of pSmad3 to a transcriptional enhancer of Foxp3 promoter, shifting Th17:Treg balance toward Th17 cells and favoring the development of autoimmunity." (PMID 33411696, 2021). "In earlier studies, we showed that these FoxP3+ T cells (both CD4+ and CD8+ Treg) suppressed autoimmunity in vivo and anti-DNA production in vitro." (PMID 34093553, 2021). "In Foxp3-DTR mice, we observed accelerated deterioration and rapid onset of autoimmunity, including increased cell death." (PMID 33208555, 2020). "Our evidence for the capacity of G-CSF-mobilized MPP to modulate autoimmunity (type 1 diabetes and EAE) through Foxp3+ Treg expansion and stabilization provides a further argument for their possible benefit during allo-HSCT." (PMID 33643294, 2020). "Tregs are a population of forkhead box P3 (Foxp3) expressed lymphocytes which suppress effector CD4+ and CD8+ T cells to prevent the development of autoimmunity, but they also suppress T cell responses during infectious diseases and different cancers." (PMID 32226027, 2020). "FOXP3-expressing Tregs, which belong to a suppressive subset of CD4+ T cells, can regulate infection, tumor development, allergy, and autoimmunity." (PMID 32040478, 2020). "In the setting of autoimmunity, the periphery of 3–4-week-old CD25cKO and CD25gKO mice contained a substantial proportion of CD4+ Foxp3+ T cells, albeit diminished in comparison with littermate controls." (PMID 30833563, 2019). "As a means of investigating the development of autoimmune disease in vivo, we made use of the fact that Foxp3-DTR mice develop spontaneous, systemic, lethal autoimmunity on depletion of Tregs by DT treatment." (PMID 30814307, 2019). "However, these two key tolerance checkpoints are unable to compensate for each other, since (i) FAS-mediated apoptosis does not control the autoimmunity that develops in FOXP3-deficient patients and (ii) Tregs do not control the autoimmunity observed in FAS-deficient patients." (PMID 29686686, 2018). "Since regulatory T cells (Treg) and the PD-1 pathway are critical in the development of autoimmunity including EAU36–38, we examined the expression of PD-1 and the Treg marker Foxp3 in HEL-specific CD4+ T cells after MCMV-HEL infection." (PMID 29079770, 2017). "Regulatory T cells (Tregs), defined as CD4+CD25+Foxp3+ or CD4+CD25+CD127low/−, mediate peripheral tolerance and prevent autoimmunity in healthy individuals." (PMID 27762298, 2016). "These are the first data to show a differential role of Foxp3+ Tregs versus Tr1 cells in limiting SR CD4+ T cells in CLN and CNS, respectively, thereby maximizing prevention of autoimmunity." (PMID 27708643, 2016). "Patients with acute GVHD (aGVHD) and chronic GVHD (cGVHD) show deficits of CD4+CD25high regulatory T (Treg) cells, which express the transcription factor, fork-head box P3 (FOXP3), and play a crucial role in control of autoimmunity." (PMID 26210500, 2015). "Mice with simultaneous Treg-specific deletion of p300 and CBP develop severe autoimmunity, as both p300 and CBP interact not only with FOXP3, but also with many FOXP3-regulating TFs including NFAT, STAT1, FOXO1, FOXO3, NF-κB, RUNX1, and STAT5." (PMID 26124919, 2015). "For example, B7 expression by B cells is required for mediating recovery in murine models of autoimmunity by mediating peak expression of IL10 and Foxp3." (PMID 23755918, 2013). "The Foxp3IRES-luciferase-IRES-eGFP (FILIG) mouse, which has a 5–10% reduction in Foxp3 expression in CD4+ T cells, develops an aggressive autoimmune disorder and wasting disease." (PMID 23345540, 2013). "The forkhead box transcription factor, Foxp3, is master regulator of the development and function of CD4+CD25+ T regulatory (Treg) cells that limit autoimmunity and maintain immune homeostasis." (PMID 22247766, 2012).
Autoimmunity (continued). "Moreover, a study evaluating self-antigen-primed T cells demonstrates how NO is able to reduce FOXP3 expression and subsequently decrease Tregs in autoimmune disorders, illustrating how intricate and vast the role of redox is in the immune response and where future studies may focus." (PMID 21647409, 2011). "Additionally, FOXP3 and IKZF4, critical for regulatory T-cell function and immune tolerance, contribute to the suppression of autoimmunity." (PMID 39860439, 2025). "FoxP3+ CD8+ Treg cells are rare under steady-state conditions in both mice and humans, but they can expand under pathological circumstances such as transplantation, autoimmunity, or cancer." (PMID 41226379, 2025). "The lack of spontaneous inflammation or autoimmunity in Ikzf1-fl-Foxp3-Cre mice is similar to mice with Treg-specific deletion of Prdm1, Icos, Il10 and Mef2d." (PMID 38655862, 2024). "Conversely, administration of CD25-blocking monoclonal antibody daclizumab led to significant and prolonged decrease in peripheral CD25+FOXP3+CD4 T cells in patients with metastatic breast cancer in the absence of autoimmunity." (PMID 39232704, 2024). "We found that low Treg cell numbers, reduced FOXP3 MFI, and altered Treg cell transcriptional profiles were not linked with clinical indication of autoimmunity, and EPF women with autoantibodies did not exhibit worse Treg cell features." (PMID 38327801, 2024). "In autoimmunity, FOXP3+ Tregs skew toward a proinflammatory, nonsuppressive phenotype and are, therefore, unable to control the exaggerated autoimmune response." (PMID 38386413, 2024). "One explanation for why the induction of Sin3a deletion did not provoke the severity of autoimmunity present in Sin3a−/−Foxp3cre is that the role of Sin3a within Foxp3+ Tregs is of vital importance during fetal and postnatal development." (PMID 39156895, 2024). "It has been proposed that ongoing autoimmunity in the EAE mouse model is likely to represent the defective function of Tregs and lose FOXP3 expression under inflammatory conditions and can be induced to express proinflammatory cytokines, such as IL-17 and IFNγ (IFNγ+ FOXP3+ IL-17A+) (52, –, 54)." (PMID 37615438, 2023). "In addition to their role in preventing autoimmunity, CD4+CD25+ T cells that express FOXP3 have been shown to be important for suppressing alloimmunity and for inducing and maintaining allograft tolerance." (PMID 37874660, 2023). "Given that Foxp3-specific ICOS ablation results in reduced numbers of Tfr cells, we investigated whether ICOS FC mice displayed signs of autoimmunity." (PMID 36754569, 2023). "Considering that Foxp3 stability is essential for maintaining Treg dynamic homoeostasis to prevent autoimmunity, the inhibitory effect of FLICR on Foxp3 May exacerbate psoriasis, which requires further elucidation." (PMID 37310201, 2023). "FOXP3 is dimethylated by PRMT5 (or PRMT1, PRMT6) at R48 and R51, which attenuates the expression of immunosuppressive genes and may lead to autoimmunity." (PMID 37143582, 2023). "Autoreactive thymocytes (T cell precursors) that recognise these TSAs with high affinity undergo negative selection via apoptosis, or, alternatively, forkhead box P3 (FOXP3)+ regulatory T cells (Treg) are generated in order to prevent autoimmunity." (PMID 36685668, 2023). "FOXP3+ regulatory T cells (Tregs) are a subset of CD4+ helper T cell lineages that function as a gatekeeper for immune activation and are essential for peripheral autoimmunity prevention." (PMID 35844606, 2022). "Foxp3+ Treg cells likewise depend on a lot of other suppressive molecules, such as IL-10, TGF-β, CD39, CD73, IL-35, and TIGIT, for their inhibitory function; most of which work by suppressing autoimmunity." (PMID 35207219, 2022). "Treg-specific deprivation of EZH2 resulted in spontaneous autoimmunity with reduced Foxp3(+) cells in nonlymphoid tissues and impaired resolution of experimental autoimmune encephalomyelitis." (PMID 35935991, 2022).
Autoimmunity (continued). "Moreover, IL-17A+Foxp3+CD4+ cells have been observed in skin lesions of patients with severe psoriasis and in experimental models of autoimmunity." (PMID 34539668, 2021). "These cells, originally described to suppress autoimmunity, are named regulatory T cells (Tregs) and represent a subset of CD4+ T helper (Th) cells expressing the forkhead box P3 (Foxp3) transcription factor as well as high levels of the interleukin (IL)-2 high-affinity receptor IL-2Rα or CD25." (PMID 33496881, 2021). "Up to date, the best characterized Th-like Treg subset in autoimmunity is the Th1-like Treg cells, with upregulated expression of transcription factor Tbet, chemokines CCR5 and CXCR3, stable Foxp3 expression due to highly demethylated TSDR region and increased production of IFN-γ cytokine." (PMID 34539668, 2021). "Given that at least two precursors give rise to several subsets of mature Foxp3+ Treg, with distinct abilities to suppress autoimmunity, it would be not surprising that a functional imprinting is acquired from Treg cell development in the thymus." (PMID 33643324, 2021). "The loss of ctla-4 in CD4+ T cells and Foxp3+ regulatory T cells was found to expand not only the effector T cells but also of CD4+Foxp3+ regulatory T cells, leading to new and unexpected insights into the function of CTLA-4 in peripheral tolerance, development of autoimmunity, and tumor immunity." (PMID 34912335, 2021). "More specifically, CD5hi human Treg preferentially express ICOS, FOXP3, GITR, and CTLA4 similar to a subpopulation of these cells in mice that are more protective in the context of tissue‐specific autoimmunity and immune homeostasis as compared to their CD5lo counterparts." (PMID 33682083, 2021). "CD4+CD25+Foxp3+ Tregs that develop in the thymus constitute 2–4% of CD4 single positive thymocytes, yet this relatively small population plays a critical role in maintaining peripheral tolerance and preventing autoimmunity." (PMID 32646440, 2020). "The absence of PD1 along with partial FoxP3 insufficiency, however, can result in Treg cells with proinflammatory properties and expansion of effector/memory T cells that contributed to the autoimmunity." (PMID 33193355, 2020). "However, excessively activated cytotoxic CD8+ T cells are prone to inducing autoimmunity, thus requiring prudent regulation by other immune cells or a subtype of CD8+FoxP3+ regulatory cells." (PMID 33374605, 2020). "Foxp3 is induced in TREG cells to limit cell cytotoxicity and autoimmunity." (PMID 32299365, 2020). "Reportedly, mice with reduced Foxp3 expression in Tregs developed multiorgan autoimmunity when Tregs also lacked PD-1 expression, suggesting that PD-1 inhibition non-redundantly controls an additional pool of autoreactive CD4+ cells." (PMID 31653839, 2019). "CD4+ CD25+ Foxp3+ regulatory T cell (Treg), another subtype of CD4+ T cell, is essential for preventing autoimmunity and maintaining lymphocyte homeostasis by contacting or releasing inhibitory cytokine like IL-10 and TGF-β on other immune cells during chronic inflammatory disease." (PMID 30800170, 2019). "In other reports, the ablation of Tregs by DT in specific pathogen-free (SPF) or germ-free adult mice led to rapid onset of lethal autoimmunity, demonstrating that many peripheral CD4+Foxp3− cells can be activated by tissue-derived autoantigens unless these cells are stopped by Tregs17,18." (PMID 31653839, 2019). "Although CD4+CD25+FoxP3+ Tregs are a major subset of Tregs, mounting evidence has shown that CD8+CD122+ T cells also are Tregs that suppress T cell responses and autoimmunity." (PMID 30863408, 2019). "In addition, we reported that IL-2-induced STAT5 activation limits Th17 differentiation and related autoimmunity in a murine model via competing the IL-6-induced STAT3 binding to the Il17a/f locus, in a FOXP3-independent fashion." (PMID 30150979, 2018).
Autoimmunity (continued). "In contrast, the conditional deletion of RelB in Foxp3+ Tregs does not alter the number and function of this subset, even though the germline deletion of RelB induces autoimmunity and an expansion of Foxp3+ Tregs, mainly due to T cell-extrinsic mechanisms." (PMID 30364244, 2018). "This study also showed that CCL1 was upregulated by FOXP3+ Treg in the CNS in an EAE mouse model of multiple sclerosis, driving a feed-forward loop in which CCR8 expression was upregulated, in turn promoting Treg-mediated suppression of autoimmunity." (PMID 30024927, 2018). "Other, non-canonical FOXP3+ T cells, such as FOXP3+CD127lowCD25low population, are also prevalent in autoimmunity and likely to be involved in FOXP3 turnover as well." (PMID 29881372, 2018). "In the mouse, a lack of CD4+ Foxp3+ Tregs results in increased autoimmunity, and adoptive transfer of Tregs prevents and reverses autoimmunity." (PMID 30037796, 2018). "In the mouse, a lack of CD4+ FoxP3+ Tregs resulted in increased autoimmunity, and adoptive transfer of Treg prevented and reversed autoimmunity." (PMID 28621034, 2017). "In humans, lack of functional Tregs also leads to autoimmunity, as is seen in individuals who have immune‐dysregulative polyendocrinopathy and enteropathy X‐linked (IPEX) syndrome due to mutations in FoxP3." (PMID 28621034, 2017). "Mutations in the Foxp3 locus (IPEX in humans and Scurfy in mice) lead to multiorgan autoimmunity and demonstrate a non-redundant role of Foxp3 in maintaining tolerance." (PMID 29259578, 2017). "Perhaps the clearest evidence for a vital role in preventing autoimmunity has been found for a population of CD4+ T cells defined by constitutive expression of high levels of CD25 (the IL-2 receptor α chain) and expression of the transcription factor FOXP3." (PMID 28770318, 2017). "For example, in infection with the helminth S. mansoni, a regulatory cascade is generated through soluble egg antigens (SEA) that induce T cell differentiation into Foxp3+ Tregs; the effect is sufficient to protect diabetes prone NOD mice from developing autoimmunity." (PMID 26617281, 2016). "CD4+ CD25+ Foxp3+ Treg is a critical sub-population of CD4+ T cells that is essential for maintaining self tolerance and preventing autoimmunity, for limiting chronic inflammatory diseases, such as asthma and inflammatory bowel disease and for regulating homeostatic lymphocyte expansion." (PMID 26884314, 2016). "In the thymus, medullary thymic epithelial cells (mTEC) regulate T cell tolerance via negative selection and Foxp3+ regulatory T cell (Treg) development, and alterations in the mTEC compartment can lead to tolerance breakdown and autoimmunity." (PMID 26254339, 2015). "In this study, insB9–23/IFA immunization controlled the recurrence of autoimmunity also via FOXP3+ Treg cells, although it did not significantly increase their number." (PMID 26080071, 2015). "Similarly, although CD4+Foxp3+ Tregs are known to control lymphoproliferation and autoimmunity, examination of LPR lymph node CD4+ T cells revealed that FcRγ-expressing cells were distinct from the Foxp3+ population." (PMID 23762329, 2013). "This would explain why fatal autoimmunity occurs when disrupting non-redundant layers of tolerance (such as Foxp3+ Tregs) while DCs remain present." (PMID 22783257, 2012). "CD4+CD25+ Treg cells can play a critical role in the prevention of autoimmunity, as evidenced by the cataclysmic autoimmune disease that develops in mice and humans lacking the key transcription factor Foxp3." (PMID 23133752, 2012). "Naturally occurring CD4+CD25+ FOXP3+ regulatory T-cells (nTREG) are a subpopulation of CD4 T-cells capable of suppressing the activation and expansion of T-effector cells, thereby inhibiting the onset of autoimmunity." (PMID 23118856, 2012). "Tr1 cells are regulatory T cells that do not express Foxp3 and suppress tissue inflammation, graft-versus-host disease and autoimmunity in an IL-10 dependent manner." (PMID 21886804, 2011).